MAPT (microtubule associated protein tau)
Diseases named in the same sentence as MAPT in open-access papers (continued):
Sharing a sentence is not in itself a finding about the gene and the disease.
neurodegenerative disease (continued). "We demonstrate that the hemizygous deletion of the endogenous SVA_67 in CRISPR edited cell lines was associated with differential expression of several genes at the MAPT locus associated with neurodegenerative diseases including KANSL1, MAPT and LRRC37A." (PMID 37840928, 2023). "The chromosomal region 17q21.31 harbors a 900 kb inversion polymorphism, named after one of the most studied genes in this region because of its plausible association with several neurodegenerative diseases: the microtubule-associated tau protein (MAPT) gene." (PMID 36355195, 2023). "The STH gene is a polymorphic gene nested within an intron of the MAPT gene and encodes the protein Saitohin, which has been found to be susceptible to multiple degenerative diseases and neuropsychiatric disorders." (PMID 40729198, 2023). "The regulation of exon 10 expression is the most investigated splicing mechanism of MAPT transcripts due to its association with neurodegenerative diseases." (PMID 36499709, 2022). "AD is a neurodegenerative disease characterized by a set of hallmark brain lesions, such as aggregation of the hyperphosphorylated MAPT (tau) protein in neurofibrillary tangles, β-amyloid aggregation in fibrillary plaques, and a neuro-inflammatory response." (PMID 35624787, 2022). "Anomalous aggregation of microtubule associated tau protein (MAPT) is a prominent pathological feature in various neurodegenerative diseases including AD." (PMID 36561136, 2022). "Having identified the major cell types, we focused on effects of MAPT mutations on the population corresponding to pyramidal neurons (EN-Ps), as they are heavily impaired in neurodegenerative diseases." (PMID 35985329, 2022). "The gene MAPT has been long implicated in neurodegenerative diseases caused by aggregation of the encoded microtubule-associated protein tau, which promotes assembly and stabilization of cytoskeletal microtubules." (PMID 35694745, 2022). "Tauopathies are a heterogenous family of progressive neurodegenerative diseases defined by the appearance of proteinaceous lesions within the brain composed of abnormally folded species of Microtubule Associated Protein Tau (tau)." (PMID 34095227, 2021). "Microtubule-associated protein tau (MAPT) is considered a significant risk factor for neurodegenerative diseases, including PD." (PMID 33804213, 2021). "Since the MAPT haplotype has been reported a major risk factor for several neurodegenerative diseases, several studies have tried to understand the underlying mechanism, with MAPT being the predominant gene of interest." (PMID 34532319, 2021). "The pathogenic role of tau in neurodegenerative disease has been confirmed by the identification of MAPT mutations and polymorphisms in patients with frontotemporal dementia with parkinsonism-17." (PMID 34753506, 2021). "Although the majority of cases of these neurodegenerative diseases are sporadic, a large number of familial mutations of the tau-encoding gene MAPT, such as P301L and K369I have been associated with tauopathies, e.g. FTD and Pick’s disease." (PMID 34147135, 2021). "Microtubule-associated protein tau (MAPT) is a protein that forms pathological aggregates in several neurodegenerative diseases." (PMID 34616286, 2021). "While the associations of MAPT haplotypes and neurodegenerative diseases are well established, the functional mechanism behind these associations is not clear." (PMID 33804213, 2021). "Microtubule-associated protein tau (MAPT) has been appointed as one of the most important risk factors for several neurodegenerative diseases including PD." (PMID 33343949, 2020). "MAPT variants have been implicated in the etiology and pathogenesis of multiple neurodegenerative diseases." (PMID 32400971, 2020). "Although MAPT is a compelling candidate for neurodegenerative disease susceptibility, evidence of association of AD with the MAPT H1 and H2 haplotypes have produced equivocal results." (PMID 32400971, 2020).
neurodegenerative disease (continued). "Tau is encoded by the microtubule-associated protein tau (MAPT) gene and causes neurodegenerative diseases referred to as tauopathies including some forms of Alzheimer." (PMID 32323160, 2020). "The aggregation of one of these client proteins, the microtubule-associated protein tau (tau), is thought to contribute to disease progression in multiple neurodegenerative diseases, including Alzheimer’s disease (AD) and frontotemporal dementia (FTD)." (PMID 32751642, 2020). "AD is the most common neurodegenerative disease and is characterized by the accumulation of amyloid-β (Aβ) along with aggregated forms of the microtubule-associated protein tau within the brain." (PMID 31911834, 2020). "Assembly of microtubule-associated protein tau into filamentous inclusions underlies a range of neurodegenerative diseases." (PMID 30720432, 2019). "Mutations in the MAPT gene, which encodes the tau protein, are associated with several neurodegenerative diseases, including frontotemporal dementia (FTD), dementia with epilepsy, and other types of dementia." (PMID 30696811, 2019). "Tau (encoded by the MAPT gene) is hyperphosphorylated and aggregates in a class of neurodegenerative diseases termed Tauopathies, which includes a subset of FTD cases lacking abnormal TDP-43 inclusions." (PMID 31036086, 2019). "PRKN, with MAPT, is the neurodegenerative disease-associated gene with the most abundant number of antisense genes and alternative antisense TSSs." (PMID 30610612, 2019). "There are currently 54 identified pathogenic MAPT mutations associated with the onset of neurodegenerative diseases, including FTD." (PMID 29890743, 2018). "The microtubule associated protein tau plays a critical role in the pathogenesis of neurodegenerative disease." (PMID 29634760, 2018). "Pathological inclusions of cytoskeletal proteins, such as neuronal intermediate filament (IF) proteins or the microtubule-associated protein tau (MAPT), are neuropathological signatures in various neurodegenerative diseases." (PMID 29947927, 2018). "Our meta-analyses provide confirmatory evidence that multiple variants in MAPT are associated with neurodegenerative diseases risk." (PMID 28402959, 2017). "The H1 haplotype of the microtubule-associated protein tau (MAPT) locus is genetically associated with neurodegenerative diseases, including Parkinson's disease (PD), and affects gene expression and splicing." (PMID 28689993, 2017). "Here we analyze these variants in MAPT and their association with neurodegenerative diseases as a step toward determining the precise mechanisms of genetic susceptibility for these group diseases." (PMID 28402959, 2017). "Our findings provide confirmatory evidence that multiple variants in distinct regions in MAPT are associated with different neurodegenerative diseases." (PMID 28402959, 2017). "In conclusion, MAPT is associated with risk of neurodegenerative diseases, suggesting crucial roles of tau in neurodegenerative processes." (PMID 28402959, 2017). "Our results robustly confirm the susceptibility role of MAPT in neurodegenerative diseases in a large meta-analysis, using highly informative htSNPs which capture 95% of MAPT haplotype diversity." (PMID 28402959, 2017). "In conclusion, this is the first comprehensive meta-analysis and systematic review which focused on the association between MAPT polymorphisms and neurodegenerative diseases so far." (PMID 28402959, 2017). "Many human neurodegenerative diseases are associated with hyperphosphorylation and widespread intra-neuronal and glial associated aggregation of the microtubule associated protein tau." (PMID 26091261, 2015). "Human mutations in the tau gene (MAPT), on their own, can also give rise to a group of neurodegenerative diseases referred to as frontotemporal dementia linked to chromosome-17 (FTDP-17), one group of a number of different types of tauopathy." (PMID 25344697, 2014).
neurodegenerative disease (continued). "Pathological hyperphosphorylation and aggregation of microtubule-associated protein tau is a common character of many neurodegenerative diseases with axonal degeneration including MS." (PMID 25150364, 2014). "Several neurodegenerative diseases are characterized by inclusions of hyperphosphorylated forms of the microtubule-associated protein tau." (PMID 22518139, 2012). "Another gene implicated in multiple neurodegenerative diseases, which was investigated with the expression endophenotype approach, is microtubule associated protein tau (MAPT)." (PMID 21569597, 2011). "Positive association studies of MAPT and neurodegenerative diseases divide the MAPT locus into two divergent clades, H1 and H2, with H2 being a single haplotype covering several genes on the long arm of chromosome 17." (PMID 17266761, 2007). "Similarly, presence of the microtubule-associated protein tau (MAPT) H1/H1 genotype has been linked to a higher predisposition to neurodegenerative diseases." (PMID 40274643, 2025). "Future research should focus on understanding the structural complexity of the 17q21.31 region, utilizing long-read sequencing and multi-omics approaches, and ensuring the inclusion of diverse populations to gain a more comprehensive understanding of MAPT-related neurodegenerative disease risk." (PMID 41472865, 2025). "MAPT mutations associated with neurodegenerative diseases may play a role in enhancing TAU aggregation, disruption of TAU protein structure, and/or interfering with mRNA splicing of MAPT." (PMID 38554150, 2024). "In addition to the MAPT and ApoE genes, numerous genetic variants have been associated with the abnormal aggregation of tau protein and the development of neurodegenerative diseases." (PMID 38930877, 2024). "Tau/MAPT (microtubule associated protein tau) protein is actively studied for the pathologic consequences of its aberrant proteostasis in central nervous system leading to neurodegenerative diseases." (PMID 37000265, 2023). "Notably, some of the BA genes we identified, such as MAP2 and MAPT known for their involvement in brain asymmetry and neurodegenerative diseases, have also been implicated in previous studies." (PMID 37561991, 2023). "Intriguingly, specific pathogenic variants in PRNP and MAPT—genes which are more commonly associated with other neurodegenerative diseases—may provide unexpectedly important insights into the formation of AD tau pathology." (PMID 35393555, 2022). "Mutations in MAPT have been shown to accelerate the aggregation of markers of neurotoxic hyperphosphorylated tau in response to repetitive concussions by 20–60% in animal studies and are associated with neurodegenerative diseases in humans." (PMID 35627205, 2022). "Currently, over 50 mutations in the MAPT gene have been correlated with neurodegenerative diseases." (PMID 35392986, 2022). "Neurodegenerative disease such as AD is characterized by the microtubule-associated neuronal protein MAPT that undergoes hyperphosphorylation by multiple kinases resulting in microtubule disintegration, and this phosphorylation can be regulated by several phosphatases, including PP2C." (PMID 35804531, 2022). "We previously identified mRNA transcripts regulated by ZC3H14–THOC binding in which dysfunction is linked to neurodegenerative disease, including postsynaptic density protein 95 (Psd95), ATP synthase lipid-binding protein (Atp5g1), and microtubule-associated protein tau (MAPT)." (PMID 33234594, 2021). "Examination of MAPT H1 subhaplotypes provides the opportunity to better understand any notable association involving the H1 haplotype, and indeed several studies have observed associations between MAPT H1 subhaplotypes and various neurodegenerative diseases." (PMID 33287913, 2020). "The microtubule-associated protein tau is a major concern in neurodegenerative diseases such as AD." (PMID 31248062, 2019).
neurodegenerative disease (continued). "Therefore, our findings suggest that Tau/MAPT, and some other genes whose alterations are linked to neurodegenerative diseases, are enriched in the less aggressive gliomas and they probably need to be downregulated for these tumors to progress." (PMID 31551755, 2019). "To date, nearly 60 mutations in MAPT have been proved pathogenic to neurodegenerative diseases." (PMID 28402959, 2017). "Therefore, we performed a meta-analysis by pooling the whole related data from previously studies to reach a more precise estimate of the relationship between variants in MAPT and their risk on neurodegenerative diseases." (PMID 28402959, 2017). "Moreover, Tau, which is also known as microtubule-associated protein tau (Mapt), is abundant in neurons and plays a critical role in neurodegenerative diseases." (PMID 26492191, 2015). "Some familial neurodegenerative diseases have been linked to tau gene (MAPT) mutations that lead to alternative splicing, changes in phosphorylation state, reduced affinity for tubulin, and (or) enhanced capacity for self-association into filaments and aggregates." (PMID 24618580, 2014). "Due to the proposed interactions of α-synuclein and tau protein and their abnormal intracellular aggregation in neurodegenerative diseases, the analysis of microtubule-associated protein tau (MAPT) gene as a genetic susceptibility factor for PD has been of interest." (PMID 19558713, 2009). "Tau is a microtubule-associated protein, encoded by the MAPT gene, which becomes abnormally phosphorylated leading to aggregation and formation of intracellular filamentous inclusions, consisting of hyperphosphorylated tau, in several neurodegenerative diseases." (PMID 39975316, 2025). "Furthermore, they hypothesized that genetic risk factors for neurodegenerative disease at the MAPT site may play a role by altering mRNA splicing in different areas of the brain, rather than by the overall expression of the MAPT gene." (PMID 32090979, 2020). "Given that PSP, PD, and FTD are neuropathologically characterized by degeneration in the midbrain, cerebellum, and (to a lesser extent) neocortical regions, our findings may suggest that subtle alterations of CXCR4 and MAPT may predispose to regionally specific brain degeneration in later life." (PMID 29636460, 2018). "Therefore, hnRNP F and hnRNP Q may play a role in modulating MAPT neurodegenerative disease-associated susceptibility." (PMID 29084565, 2017). "Importantly, the discovery of multiple tau gene mutations in people with frontotemporal dementia exhibiting neuropathological evidence of FTLD-tau has shown that certain MAPT mutations result in abnormalities in tau protein that cause neurodegenerative disease." (PMID 28386764, 2017). "The MAPT locus is known to be susceptible to microduplications and microdeletions, and an ancestral inverted H2 haplotype predominant in European Causasians contrasts with the direct-oriented H1 haplotype more closely associated with neurodegenerative diseases." (PMID 27030133, 2016). "AD is a degenerative disease manifesting in the brain, and its cause has been hypothesized to be the formation of protein aggregates leading to neuron death, in particular related to the abnormal phosphorylation of the microtubule-associated protein tau." (PMID 23300433, 2013). "This analysis further validates our previous research, illustrating the functional capacity of SVA_67 within neurodegenerative diseases and potentially expanding the importance of SVA_67 and the MAPT locus to ALS." (PMID 38540776, 2024). "Our research has centered on the microtubule-associated protein tau (MAPT), a crucial pathological protein implicated in neurodegenerative diseases, and its interplay with neurons’ DNA damage response (DDR)." (PMID 39063148, 2024).
neurodegenerative disease (continued). "We found three clusters defined mainly by genetic variants found in MAPT, APP, and APOE, considering known variants associated with AD and other neurodegenerative disease genetic architectures." (PMID 38693203, 2024). "A meta-analysis of genome-wide association studies identified ancestry-specific associations underlying circulating total tau levels, indicating an important role of MAPT in many neurodegenerative diseases." (PMID 38930877, 2024). "In the sections that follow, we highlight associations of several genes (e.g., MAPT, PRNP, GRN) with clinical EOAD that are better known for their role in other neurodegenerative diseases." (PMID 35393555, 2022). "MAPT gene mutations lead to Tau hyperphosphorylation (p-Tau) and NFT deposition in the brains and cause genetic forms of neurodegenerative diseases." (PMID 35662233, 2022). "Mutations in the Microtubule Associated Protein Tau (MAPT) gene, which encodes the Tau protein, are known to be related to a number of neurodegenerative diseases." (PMID 36408110, 2022). "In brains with neurodegenerative disease, astrocytes that express MAPT do so at higher levels than control brain astrocytes." (PMID 33757579, 2021). "The involvement of APP and MAPT in certain neurodegenerative diseases, ageing, and most importantly, in TBI is well documented and supportive of our findings." (PMID 34572074, 2021). "There is somewhat more evidence regarding the role of MAPT haplotypes (H1 and H2) in neurodegenerative diseases." (PMID 33329348, 2020). "Similar to APP/MAPT transgenic mice, most other neurodegenerative disease mouse models strongly activated expression signatures overlapping with the cluster B and cluster C modules from human brain." (PMID 32668255, 2020). "About half of the neurodegenerative disease-associated genes, namely APP, PSEN1, and PSEN2 for AD; C9orf72 and MAPT for FTD and SNCA; and PRKN and PARK7 for PD, have larger number of DPI robust TSSs than annotated CAT CAGE clusters." (PMID 30610612, 2019). "TAU protein, another important factor in neurodegenerative diseases, is encoded by MAPT (microtubule associated protein tau) gene." (PMID 31249505, 2019). "This fits well to earlier work in neurodegenerative diseases reporting that PTEN can affect MAPT phosphorylation, aggregation or it’s binding to microtubules." (PMID 30823906, 2019). "No additional pathogenic mutations were found in other dominant causative genes of AD, FTD, or of other neurodegenerative diseases, such as APP, PSEN2, PRNP, PGRN, or MAPT." (PMID 30917570, 2019). "No additional pathogenic mutations were identified in other dominant causative genes of AD, FTD, or of other neurodegenerative diseases, such as PSEN1, PSEN2, PGRN, or MAPT on this patient." (PMID 30917570, 2019). "Three of the genes, GPR37, MAPT and PSENEN observed interacting with all three BPA, E2, and NRF1 are associated with neurodegenerative disease." (PMID 27983596, 2016). "Three of the common E2 and NRF1 target genes, GPR37, MAPT, and PSENEN are associated with neurodegenerative disease." (PMID 27983596, 2016). "Two of the genes, MAPT and PSENEN, observed interacting with all three EE, E2 and NRF1 are associated with neurodegenerative disease." (PMID 27983596, 2016). "This mutation was transmitted with a recessive pattern of inheritance, the only example for MAPT and one of the very few cases in neurodegenerative diseases." (PMID 26528178, 2015). "In fact, a subset of neurodegenerative diseases known as tauopathies, are associated with the accumulation of tau without amyloid accumulation, with mutations within the MAPT gene leading to familial forms of tauopathy." (PMID 36970154, 2023). "Therefore, this study highlighted an additional type of variation to be considered at the MAPT locus and an added layer of complexity when analysing the missing heritability of neurodegenerative diseases." (PMID 35370538, 2022).